Y_RNA (Y RNA )
Gene: Miscellaneous RNA gene on chromosome 1 (85,264,296 to 85,264,402, forward strand). Ensembl gene ENSG00000223254.
Homologues: Paralogues in human: Y_RNA (79% identical), RNY1 (79% identical), Y_RNA (78% identical), Y_RNA (77% identical), Y_RNA (76% identical), RNY1P8 (75% identical), Y_RNA (75% identical), Y_RNA (74% identical), RNY1P11 (73% identical), RNY1P7 (73% identical), Y_RNA (73% identical), RNY1P10 (72% identical), and 91 more.